RNU2-36P (RNA, U2 small nuclear 36, pseudogene)
Gene: Small nuclear RNA gene on chromosome 9 (86,422,938 to 86,423,128, reverse strand). Ensembl gene ENSG00000222293.
Homologues: Orthologues: chimpanzee U2 (98% identical), pig U2 (85% identical), guinea pig U2 (81% identical), guinea pig U2 (54% identical), dog U2 (27% identical). Paralogues in human: RNU2-59P (88% identical), RNU2-2 (86% identical), RNU2-14P (85% identical), U2 (84% identical), RNU2-26P (83% identical), RNU2-57P (83% identical), RNU2-3P (82% identical), RNU2-23P (82% identical), RNU2-4P (81% identical), RNU2-20P (80% identical), RNU2-6P (80% identical), RNU2-64P (80% identical), and 64 more.